CD38 (CD38 molecule)
Diseases named in the same sentence as CD38 in open-access papers (continued):
Sharing a sentence is not in itself a finding about the gene and the disease.
multiple myeloma (continued). "For example, as multiple myeloma cells are marked by CD38+/CD138+ antigen expression, they could be distinguished by the codetection of high CD138 (SDC1) and CD38 gene expression in scRNA-seq data." (PMID 32929226, 2020). "Two receptors, CD38 and CD138, have recently garnered much interest for multiple myeloma." (PMID 33138841, 2020). "Phase 1 studies are currently enrolling patients with multiple myeloma to evaluate the safety and efficacy of either single CAR T cell products targeting BCMA, CD138, CD38, Integrin β7 or CS1, or ten different dual-targeting combinations of these products (NCT03778346)." (PMID 32899464, 2020). "CD38 is expressed in several hematological malignancies, including acute B lymphoblastic leukemia (B-ALL), acute myeloid leukemia (AML), mantle cell lymphoma (MCL), chronic lymphocytic leukemia (CLL), multiple myeloma (MM) and NK/T cell leukemia (T-ALL)." (PMID 31636635, 2019). "On the contrary, the in vitro continuous exposure of myeloma cells to effective concentrations of isatuximab does not result in a decrease of surface CD38." (PMID 31766279, 2019). "The interest in CD38 as a tumor-promoting molecule has grown as more research expands the field, originating in hematological diseases such as chronic lymphocytic leukemia (CLL) and multiple myeloma, but now blossoming into multiple types of solid tumors." (PMID 31878283, 2019). "In the case of MM, the increase in CD38 expression after panobinostat treatment was specific for myeloma and was not evident in lymphoma cell lines." (PMID 31067680, 2019). "CD38 is used as a disease marker for leukemia and myeloma and it is considered a negative prognostic marker for CLL." (PMID 31118070, 2019). "Both HD-ASC and MM-ASC expressed very low levels of CD34, while CD38 expression was negative in both cases, indicating that the cell cultures contained no myeloma cells (data not shown)." (PMID 31083455, 2019). "Correlation of CD38-expression with prognostic clinical parameters was neither observed in symptomatic nor asymptomatic myeloma patients in more than one assessment of CD38-expression." (PMID 30079070, 2018). "In vivo, relapsed myeloma patients reaching a partial remission or better vs. responding less to daratumumab-treatment show higher CD38-expression on myeloma cells, but no “threshold” for anti-CD38 activity was found." (PMID 30079070, 2018). "By tandem fusion of two nanobodies that recognize independent epitopes of CD38 to the Fc domain of human IgG, we recently generated tetravalent biparatopic hcAbs that exhibit a markedly enhanced capacity to induce CDC of CD38-expressing myeloma cells." (PMID 30459772, 2018). "The availability of two antibodies targeting distinct myeloma cell surface markers (SLAMF7 and CD38, respectively) provides an advantage that could be exploited in treating MM patients." (PMID 30455698, 2018). "Set out to develop an efficient CAR T cell therapy for multiple myeloma (MM) we also have recently investigated and demonstrated the possibility to target MM cells with CAR T cells directed against the CD38 antigen, which is highly and uniformly expressed on MM cells." (PMID 29847570, 2018). "Cluster of differentiation 38 (CD38), which is a glycoprotein functioning in cell adhesion, signal transduction and calcium signaling, is highly expressed on myeloma cells, but at relatively low levels on normal hematopoietic cells and in some tissues of non-hematopoietic origin, like lung tissue." (PMID 27900520, 2017). "While bortezomib treatment slightly affected the ratio of CD38+/CD138Bright MM cells, it failed to induce apoptosis on myeloma cells with 8p21 deletion, either alone or in combination with soluble TRAIL/APO2L." (PMID 26378933, 2015). "Still to be analyzed in depth are the events following CD38 ligation and the induction of MV, which seem not to be just innocent bystanders in human myeloma." (PMID 26393653, 2015).
multiple myeloma (continued). "Immunophenotypic analysis of the myeloma cells confirmed strong expression of plasma cell markers CD38 and CD138 but not T-cell or natural killer-cell marker CD56." (PMID 24330858, 2013). "Expression of sclerostin in human myeloma cellline (U266) was evaluated as myeloma cells withmyeloma markers (CD38+, CD138+, CD19-) andT293 and K562 as negative control." (PMID 24027669, 2013). "Adult patients with relapsed or refractory multiple myeloma who had previously received at least 3 prior therapies, including a proteasome inhibitor, an immunomodulatory agent, and an anti-CD38 monoclonal antibody, and had not received prior BCMA-targeted therapy." (PMID 40626006, 2025). "Notably, anti‐CD38 mAbs, Daratumumab (Dara) and Isatuximab (Isa) have demonstrated substantial efficacy, which has led to their initial FDA approval for relapsed/refractory multiple myeloma (RRMM)." (PMID 40176408, 2025). "Daratumumab, the first anti-CD38 monoclonal antibody to be given approval both for patients with newly diagnosed MM (NDMM) and relapsed/refractory MM (RRMM), is now a backbone of MM patient management, having shown significant efficacy when combined with other standard anti-myeloma regimens." (PMID 40563593, 2025). "Briefly, it binds with high affinity to a specific CD38 epitope on CD38-expressing MM cells and induces complement-dependent cytotoxicity (CDC), antibody-dependent cell-mediated cytotoxicity (ADCC), and antibody-dependent cellular phagocytosis (ADCP) against myeloma cells." (PMID 39518146, 2024). "In addition to the activity on myeloma plasma cells, T cells may be engaged through all three targets, CD3, CD28, and CD38." (PMID 38786100, 2024). "Given the important role of XBP1 splicing in myeloma plasma cells, future work will investigate the role spliced vs unspliced XBP1 in specifically regulating CD38, because this strategy may provide new avenues for CD38 manipulation." (PMID 40453054, 2024). "•CD38 knockdown does not lead to broad myeloma cell surface remodeling." (PMID 40453054, 2024). "CD38-expressing malignant B cells and long-lived PCs can be targeted by novel B cell–targeted therapies such as the anti-CD38 mAbs daratumumab (DARA, trade name Darzalex) or isatuximab (trade name Sarclisa), which are currently approved for treatment of multiple myeloma (MM)." (PMID 37419630, 2023). "The first-in-class mAb to target MM was Daratumumab, an anti-CD38 mAb which was shown to facilitate lysis of MM plasma cells through various antibody-mediated mechanisms such as ADCC, CDC, and ADCP, significantly improving the outcomes of patients with relapsed or refractory myeloma." (PMID 38139060, 2023). "In conclusion, by combining phage display, cellular panning and NGS analyses of an immune library, we successfully identified two novel CD38 and ICAM-1 antibodies, and at least 7 antibodies targeting yet unknown, potentially novel antigens on myeloma cell surface." (PMID 35784366, 2022). "Although CD38 is not highly expressed by osteoblasts, our results point towards an indirect effect of daratumumab inducing bone formation, which is mediated by both an anti-myeloma effect and a decrease in inhibitors of osteoblast activity." (PMID 35681747, 2022). "Idecaptagene-vicleucel (bb2121) is an anti-BCMA chimeric antigen receptor T-cell therapy for the treatment of multiple myeloma, approved by the FDA in 2021 for the treatment of adults with relapsed or refractory multiple myeloma, who have received at least three lines of anti-CD38/PI/IMID treatment." (PMID 35723356, 2022). "Whether selinexor can also promote ADCC in combination with anti-CD38 antibodies such as daratumumab has not yet been investigated however represents an opportunity in multiple myeloma." (PMID 36560403, 2022).
multiple myeloma (continued). "Notably, across these lines we detected almost all of the major immunotherapy targets in myeloma, as well as canonical flow cytometry markers for plasma cells: BCMA, CD138/SDC1, CD38, CD56, SLAMF7/CS-1, CD46, Integrin-b7 (ITGB7), CD74/HLA-DR, TACI, CD48/SLAMF2, and LY9/CD229." (PMID 35840578, 2022). "Interestingly, this upregulation in CD38 expression levels was only observed in myeloma cells, not in T cells, and also lymphoma cell lines." (PMID 36139103, 2022). "EVs from the PB of newly diagnosed multiple myeloma (NDMM) patients had a lower level of CD38 (median MFI = 610.45), but not significantly different from patients who had received DARA, p = 0.07, however it should be noted that the sample size of NDMM is only four patients." (PMID 36359760, 2022). "Interestingly, while daratumumab has been shown to induce the release of CD38 from the surface of myeloma cells, this was not seen with isatuximab." (PMID 34638271, 2021). "It is noteworthy, however, that CD38 is generally not highly expressed on myeloma cells and its expression can be downregulated in advanced disease;67,68 thus, resistance to the anti-CD38-CAR-T may be expected." (PMID 33927192, 2021). "In addition to the incorporation of anti-CD38 antibodies into standard of care, CAR-T cell therapy and bispecific T-cell engaging antibodies have emerged as particularly promising treatments poised to define a new wave of myeloma-directed therapeutics." (PMID 35127532, 2021). "The anti-myeloma activity of daratumumab is mediated by a diverse range of mechanisms including antibody-dependent cellular cytotoxicity (ADCC) and phagocytosis, complement-dependent cytotoxicity (CDC), apoptosis and inhibition of the enzymatic effects of CD38." (PMID 33922567, 2021). "To better assess the inhibitory potency of CD38-specific antibodies, here we report the successful adaptation of HPLC and fluorimetric assays to monitor the enzyme activity of living CD38-expressing tumor cells, i.e., CD38-transfected HEK cells and the LP-1 multiple myeloma cell line." (PMID 33396591, 2020). "Second-generation novel agents like carfilzomib and pomalidomide, anti-CD38 monoclonal antibodies, and anti-SLAM7 monoclonal antibodies have proven therapeutic efficacy and have been incorporated in current clinical practice, forming the current landscape for multiple myeloma treatment." (PMID 32411240, 2020). "In 2009, we proposed CD38 as a MM target in virtue of its expression: it is absent on early hematological progenitors, has variable but generalized limited expression by normal cells, but is extremely high in plasma cells and in myeloma." (PMID 33096610, 2020). "The survival of patients with multiple myeloma (MM) has been dramatically improved in the last decade thanks to the incorporation of second-generation proteasome inhibitors (PI), immunomodulatory drugs (IMID), and, more recently, anti-CD38 monoclonal antibodies (MoAb)." (PMID 33172026, 2020). "In addition, panobinostat, a pan-histone deacetylase inhibitor with intrinsic anti-myeloma activity, was also shown to increase CD38 expression on MM cells, leading to increased ADCC (but not CDC) of primary MM cells induced by daratumumab." (PMID 32331242, 2020). "Lastly, CD38 is a widespread antigen which is present on the surface of activated B lymphocytes and may thus be used as the antigenic target for cellular therapies (i.e., CAR-T cells) not only in multiple myeloma but also in non-Hodgkin lymphoma." (PMID 32225002, 2020). "Furthermore, in an in vitro myeloma cancer model, myeloma cells were shown to receive mitochondria from non-malignant bone marrow stromal cells through CD-38-dependent tumor-derived formation of TNTs." (PMID 32197663, 2020).
multiple myeloma (continued). "Identification of CD38 and SLAMF7 as suitable therapeutic targets because of their high expression on the surfaces of malignant plasma cells led to the development of daratumumab and elotuzumab, respectively, both of which received FDA approval as anti-myeloma agents three years ago." (PMID 30544512, 2018). "Following the demonstration of promising preclinical and clinical activities, two monoclonal antibodies targeting CD38 (daratumumab) and SLAMF7 (elotuzumab) were approved by the Food and Drug Administration (FDA) to treat patients with relapsed and refractory multiple myeloma in late 2015." (PMID 31548533, 2017). "Most advanced is the recruitment of innate immunity to kill myeloma cells by monoclonal antibodies targeting antigens either aberrantly expressed on myeloma cells (e.g. SLAMF7 -elotuzumab) or expressed on both, normal as well as malignant plasma cells (e.g. CD38 -daratumumab, isatuximab)." (PMID 29156688, 2017). "More importantly, the combination of bortezomib and TRAIL treatment significantly increased apoptosis and decrease the number of CD38+/CD138Bright MM cells, implying that bortezomib treatment can further sensitize myeloma cells without 8p21 deletion to TRAIL-mediated killing." (PMID 26378933, 2015). "Despite advancements in treatment, multiple myeloma (MM) remains without a cure and nearly always develops refractoriness to the 3 primary classes of standard therapies (immunomodulatory drugs, proteasome inhibitors and anti-CD38 monoclonal antibodies (αCD38 mAbs)." (PMID 38826786, 2024). "In addition to the increase in CD38 levels, we have demonstrated that tinostamustine augments the expression of several NKG2D ligands, especially MICA and MICB, in myeloma cell lines, an event that may also be beneficial when combining tinostamustine with immunotherapy treatments." (PMID 38731936, 2024). "Despite advancements in treatment, multiple myeloma (MM) remains without a cure, nearly always developing refractoriness to 3 primary classes of standard anti-MM therapies: immunomodulatory drugs (IMiDs), proteasome inhibitors (PIs) and anti-CD38 monoclonal antibodies (αCD38 mAbs)." (PMID 38826786, 2024). "That said, although our proteomic analysis after CD38 knockdown showed limited common features across 3 myeloma cell lines, we cannot rule out that major surfaceome remodeling could truly be present but with marked variability in responsive surface proteins from line to line." (PMID 40453054, 2024). "In addition, a multi-antigen targeting strategy has been assessed for multiple myeloma, with anti-BCMA CAR-NK cells engineered with a high-affinity non-cleavable CD16 demonstrating strong efficacy in murine models of myeloma in combination with the anti-CD38 antibody daratumumab." (PMID 38223411, 2024). "Similarly, daratumumab (an anti-CD38 targeting plasma cells in multiple myeloma) could represent a therapeutic avenue if rituximab fails to deplete the entire B-cell compartment in patients with IMNM." (PMID 38390873, 2024). "To evaluate if other antigens might be preferable to BCMA for the detection of myeloma EVs, we evaluated 15 samples from 5 of the 10 patients treated with Belantamab (cycles 1 to 3) and quantified EVs with the following antigens: CD23, CD27, CD38, CD56 and CD138." (PMID 38039414, 2023). "Interestingly, while these triple-engineered iPSC-NK cells demonstrate potent anti-tumor activity in vitro, they were no better than iPSC-NK cells with just the engineered CD16 and IL15 receptor (and not the CD38-KO) in killing tumor cells in vivo using myeloma and AML xenograft models." (PMID 35185932, 2022). "Similarly, HMCL xenografts have been used to evaluate AMG 701, a half-life extended BITE that binds to BCMA on myeloma cells and CD3 on T cells, and to demonstrate that the therapeutic efficacy of daratumumab in myeloma may be enhanced when CD38 in NK cells has been deleted." (PMID 34149703, 2021).
multiple myeloma (continued). "Functionally, VitD3 and the EB-1089 analogue can reduce growth, inhibit MYC expression and increase CD38 expression by 50-400% on ABC-DLBCL and myeloma but not GC-DLBCL cells." (PMID 41884528, 2026). "Multiple myeloma patients receiving bortezomib, thalidomide and DEX with or without the anti‐CD38 monoclonal antibody, daratumumab, had no changes in DC populations in the absence of daratumumab during 12 weeks of treatment." (PMID 38034081, 2023). "To assess the total clonal myeloma population via flow cytometry, we first characterized the expression of CD138, CD38 and other markers that differentiate myeloma cells (not shown: CD19, CD27 and CD45)." (PMID 38001595, 2023). "Elotuzumab, which, unlike anti-CD38 drugs, lacks single-agent activity, works through the direct activation of SLAMF7 on both myeloma cells and NK cells to kill myeloma cells via ADCC." (PMID 37958658, 2023). "A further uncertainty, not yet clarified, concerns the likely reinforcement of the CD38-mediated mechanisms by the other ecto-ADPRC CD157, e.g., in multiple myeloma (MM) and in pleural mesothelioma cells." (PMID 36078044, 2022). "ADCs targeting BCMA, CD38, CD46, CD56, CD74, CD138 are not discussed here since this special issue contains another article devoted to ADCs in multiple myeloma, and these targets are mainly explored in this disease setting." (PMID 36654819, 2022). "Patients with relapsed and refractory multiple myeloma (RRMM) who are triple-class exposed (to an immunomodulatory agent, proteasome inhibitor, and anti-CD38 antibody) have limited treatment options and there is no standard of care." (PMID 34145225, 2021). "SLAMF3 is expressed on MM cells regardless of disease progression or cell phenotype and is detected not only on CD38+CD138+ plasma cells but also on aberrant CD56+ plasma cells and CD38+CD138low/negative chemotherapy-resistant myeloma progenitor cells." (PMID 33451089, 2021). "CD38 is known to be expressed on most AML and myeloma cells, and its lack of expression on hematopoietic stem cells (HSCs) renders it a potential therapeutic target for relapsed AML." (PMID 34034795, 2021). "In contrast, isatuximab, the second anti-CD38 mAb FDA approved for treatment of plasma cell diseases, does not appear to induce significant CDC in primary multiple myeloma cells." (PMID 33271825, 2020). "Our results further demonstrated that the number of HPCs (Lin-CD34+CD38+), but not HSCs (Lin-CD34+CD38−), was more significantly decreased in the bone marrow of myeloma and negatively correlated with the quantity of CD38+CD138+ tumour cells (r = − 0.6112)." (PMID 33239656, 2020). "The lymphocytes express the pan-B cell markers CD19 and CD20 and the plasma cells express CD138 and CD38 and often retain expression of CD19 and CD45, unlike myeloma." (PMID 31842799, 2019). "Multiple myeloma cell-derived exosomes release exosomes that are equipped with CD39/CD73 and with the enzymes that generate ADO via the non-canonical pathway (NAD+ /CD38/CD203a(PC-1)/CD73), and thus are able to generate ADO utilizing both the canonical and non-canonical pathways." (PMID 31739402, 2019). "Interestingly, the use of daratumumab, an FDA approved monoclonal antibody against CD38, in a cohort of 34 multiple myeloma patients after allo-HSCT resulted in low aGvHD (15%) and no cGvHD, suggesting that CD38 is an attractive target for the treatment of GvHD." (PMID 41159029, 2025). "However, incorporating MM antigens that are not exclusive to plasma cells and myeloma cells, particularly those strongly expressed on MM cells but with lower expression on healthy cells (e.g., CD138, CD38, and SLAMF7), can offer advantages and open new possibilities." (PMID 38438559, 2024). "Therefore, it is plausible that the decrease in the NK cell population after anti-CD38 antibody exposure may have hindered the induction of effective ADCC by elotuzumab, leading to the lack of efficacy against myeloma." (PMID 38143697, 2023).
multiple myeloma (continued). "The results show that the CD38-specific HLE-nano-BiKEs and daratumumab induced NK92 hCD16 cell mediated cytolysis of primary CD138+/CD38+ MM cells with similar efficacies, while the isotype-control HLE-nano-BiKE co did not induce NK92 hCD16 cell mediated death of primary myeloma cells." (PMID 35651607, 2022).